OR52E2 (olfactory receptor family 52 subfamily E member 2)
Description:
Odorant receptor.
Tractability: Antibody: UniProt places it where antibodies can reach, with medium confidence; UniProt predicts a signal peptide or a membrane-spanning region; its Gene Ontology location is reachable by antibodies, with medium confidence.
Gene: Protein-coding gene on chromosome 11 (5,058,650 to 5,059,627, reverse strand). Ensembl gene ENSG00000176787.
Subcellular location: Cell membrane
Pathways (Reactome):
Sensory Perception: Expression and translocation of olfactory receptors
Gene Ontology:
Molecular function: olfactory receptor activity; G protein-coupled receptor activity
Biological process: detection of chemical stimulus involved in sensory perception of smell; G protein-coupled receptor signaling pathway; nervous system process
Cellular component: plasma membrane; membrane
Genetic constraint (gnomAD): Missense variants: 413 observed, 372.42 expected, observed/expected ratio (o/e) 1.11, 90% interval 1.02 to 1.2. Synonymous variants: 121 observed, 130.11 expected, observed/expected ratio (o/e) 0.93, 90% interval 0.8 to 1.08.
Homologues: Orthologues: chimpanzee OR52E2 (98% identical), dog OR52E2 (82% identical), mouse Or52e2 (82% identical), rat Or52e2 (81% identical), tropical clawed frog or52m1 (44% identical). Paralogues in human: OR52E4 (66% identical), OR52E5 (65% identical), OR52E8 (63% identical), OR52E6 (62% identical), OR52E1 (58% identical), OR52J3 (54% identical), OR52R1 (52% identical), OR52B6 (52% identical), OR52H1 (51% identical), OR52D1 (51% identical), OR52B2 (50% identical), OR52A5 (50% identical), and 39 more.